SEC63 (SEC63 protein translocation regulator)
Description:
Mediates cotranslational and post-translational transport of certain precursor polypeptides across endoplasmic reticulum (ER). Proposed to play an auxiliary role in recognition of precursors with short and apolar signal peptides. May cooperate with SEC62 and HSPA5/BiP to facilitate targeting of small presecretory proteins into the SEC61 channel-forming translocon complex, triggering channel opening for polypeptide translocation to the ER lumen. Required for efficient PKD1/Polycystin-1 biogenesis and trafficking to the plasma membrane of the primary cilia (By similarity).
Synonyms: DNAJC23; SEC63L; PRO2507; ERdj2; PCLD2
Tractability: Antibody: UniProt predicts a signal peptide or a membrane-spanning region. PROTAC: ubiquitination databases record sites on it; its protein half-life has been measured.
Gene: Protein-coding gene on chromosome 6 (107,867,756 to 107,958,309, reverse strand). Ensembl gene ENSG00000025796.
Subcellular location: Endoplasmic reticulum membrane
Subcellular location (Human Protein Atlas): Endoplasmic reticulum
Gene Ontology:
Molecular function: protein binding; RNA binding; signaling receptor activity
Biological process: post-translational protein targeting to endoplasmic reticulum membrane; post-translational protein targeting to membrane, translocation; SRP-dependent cotranslational protein targeting to membrane; protein targeting to membrane
Cellular component: endoplasmic reticulum; membrane; Sec62/Sec63 complex; endoplasmic reticulum membrane
Genetic constraint (gnomAD): Loss-of-function variants: 18 observed, 50.22 expected, observed/expected ratio (o/e) 0.36, 90% interval 0.25 to 0.53. The upper end of that interval is the gene's LOEUF score, 0.53, which puts it in group 2 of 6, group 1 being the genes least tolerant of losing a copy. Missense variants: 358 observed, 509.14 expected, observed/expected ratio (o/e) 0.7, 90% interval 0.64 to 0.77. Synonymous variants: 160 observed, 171.93 expected, observed/expected ratio (o/e) 0.93, 90% interval 0.82 to 1.06.
Gene-disease validity (ClinGen):
ClinGen rates the evidence that SEC63 causes each of these diseases.
polycystic liver disease 2 (autosomal dominant): Definitive.
Homologues: Orthologues: macaque SEC63 (100% identical), chimpanzee SEC63 (99% identical), dog SEC63 (99% identical), pig SEC63 (99% identical), mouse Sec63 (96% identical), rat Sec63 (96% identical), guinea pig SEC63 (93% identical), rabbit SEC63 (93% identical), tropical clawed frog sec63 (83% identical), zebrafish sec63 (72% identical), Drosophila melanogaster Sec63 (44% identical), Caenorhabditis elegans dnj-29 (36% identical).
Diseases named in the same sentence as SEC63 in open-access papers:
SEC63 is named in the same sentence as 33 diseases in open-access papers, as found by Europe PMC text mining. Sharing a sentence is not in itself a finding about the gene and the disease. The quoted sentences say what the papers report.
polycystic liver disease (9 papers, 2009 to 2024). "Mutations in sec63 cause polycystic liver disease in humans, and even zebrafish sec63 mutants develop liver pathology." (PMID 31754327, 2019). "Mutations in human SEC63 lead to polycystic liver disease which in its initial stages is characterized by dilated ER cisternae indicative of accumulation of proteins in the ER lumen." (PMID 24324744, 2013). "Our work therefore suggests that yeast is not an appropriate model organism to study diseases that are caused by mutations in or altered expression of mammalian SEC63 (polycystic liver disease, certain cancers)." (PMID 24324744, 2013). "Dysfunction of the SEC63 gene is associated with defects in protein translocation into the ER and results in human diseases including various cancers and the polycystic liver disease (PCLD)." (PMID 19208265, 2009). "The diseases include SEC61A1-linked common variable immunodeficiency, neutropenia and tubulointerstitial kidney disease, SEC61B- and SEC63-linked polycystic liver disease, and TRAP-, as well as TRC35-, TRC40-, and CAML-linked congenital disorders of glycosylation." (PMID 37762469, 2023). "Mutations in the gene encoding SEC63 are tightly associated with polycystic liver disease." (PMID 37122003, 2023). "The germline mutations of SEC63 gene are associated with polycystic liver disease." (PMID 37122003, 2023). "Subsequent studies confirmed SEC63 as a driver gene in the pathogenesis of polycystic liver disease." (PMID 37122003, 2023). "Its action as a translocational controller may explain why the loss of Sec63 function associated with polycystic liver disease (PCLD) is not lethal in humans." (PMID 23166619, 2012). "Loss of function mutations in the human Sec63 are not lethal but are linked to polycystic liver disease, indicating that it may contribute to ER import and/or folding of proteins involved in biliary cell growth." (PMID 23166619, 2012). "Interestingly, the present analysis identified yet another multispanning plasma membrane protein, VANGL2, that is involved in the establishment and regulation of planar cell polarity as a Sec63 client and, when absent, may also contribute to the phenotype of SEC63-linked polycystic liver disease." (PMID 37762469, 2023). "Of note, 4 patients in the COL4A3 cohort had liver cysts and despite no potentially pathogenic variants being found in genes associated with polycystic liver disease (PRKCSH, SEC63, and LRP5), we cannot completely rule out the presence of a second variant contributing to this phenotype." (PMID 39190485, 2024).
autosomal dominant polycystic liver disease (8 papers, 2012 to 2023). An autosomal dominant inherited condition characterized by many cysts of various sizes scattered throughout the liver. "Sec63 deletion in yeast is lethal, and in humans, mutations in Sec63/Erdj2 are linked to autosomal dominant polycystic liver disease (PCLD)." (PMID 36589230, 2022). "Some liver cells, however, have been implicated in Sec63 abnormalities, as mutations in the Sec63 gene contribute to the development of autosomal dominant polycystic liver disease." (PMID 23166619, 2012). "For example, nephron-specific loss of another ER resident — SEC63, which interacts and functions with BiP — causes renal cyst proliferation in a murine autosomal dominant polycystic liver disease (ADPLD) model." (PMID 35104250, 2022). "Autosomal Dominant Polycystic Liver Disease (ADPLD) leads to PLD only and is caused by a mutation in PRKCSH, SEC63, LRP5, ALG8 or SEC61B." (PMID 35216547, 2022).
polycystic kidney disease (7 papers, 2012 to 2026). A usually autosomal dominant and less frequently autosomal recessive genetic disorder characterized by the presence of numerous cysts in the kidneys leading to end-stage renal failure. "Double knockout of Sec63 and Xbp1 enhances the severity of polycystic kidney disease in mice and re-expression of XBP1s is able to rescue the inactivation of Sec63 with XBP1 or IRE1α induced interstitial inflammation and fibrosis." (PMID 35765067, 2022). "Inactivation of Sec63 homolog, protein translocation regulator (Sec63) in all distal nephron segments results in polycystin-1–mediated polycystic kidney disease (PKD)." (PMID 35269888, 2022). "Double knockout of SEC63 and XBP-1 worsens the polycystic kidney phenotype, whereas overexpression of XBP-1 in distal tubules in SEC63-deletion mice attenuates cyst formation through enhanced biogenesis of PC-1." (PMID 33671535, 2021).
cyst (6 papers, 2012 to 2023). A sac-like closed membranous structure that may be empty or contain fluid or amorphous material. "In conclusion, we have now shown that in both PRKCSH and SEC63 somatic second-hit mutations can occur which supports the notion that somatic second-hit mutations are part of the genetic mechanism in cyst formation in PCLD." (PMID 23209713, 2012). "In conclusion, as somatic second-hit mutations also play a role in cyst formation in patients with a SEC63 germline mutation, this appears to be a general mechanism of cyst formation in PCLD." (PMID 23209713, 2012). "Consistently, loss of SEC63 in kidneys causes cyst formations." (PMID 27585985, 2016). "We therefore hypothesise that, similar to the situation in PRKCSH, somatic second-hit mutations are also an important step in cyst formation in patients with a SEC63 germline mutation." (PMID 23209713, 2012). "To this end we analysed 52 cyst samples from 3 patients carrying a SEC63 mutation." (PMID 23209713, 2012). "We hypothesise that somatic second-hit mutations are a general mechanism of cyst formation in PCLD which also plays a role in PCLD patients carrying a SEC63 germline mutation." (PMID 23209713, 2012). "Much less is known about how the heterozygous mutations in SEC63 lead to cyst formation." (PMID 23209713, 2012). "Sec63 is involved in the biogenesis of polycystin 1/2, and cyst formation in the liver is increased in Sec63 defective mice." (PMID 34884562, 2021). "Immunostaining of SEC63 and hepatocystin showed that the hepatocystin staining was similar between cysts, whereas for SEC63 the intensity of the staining was reduced in the cyst with LOH but appears normal in the cysts without loss of heterozygosity." (PMID 23209713, 2012). "Furthermore, no loss of SEC63 protein has been reported in cysts form patients with a germline mutation in this gene, which could reflect a different mechanism of cyst development in cysts from SEC63 patients." (PMID 23209713, 2012).
Renal cyst (5 papers, 2017 to 2026). A fluid filled sac in the kidney. "While SEC63 mutations rarely involve the kidneys, the co-existence of an IFT140 variant likely contributed to the development of bilateral renal cysts." (PMID 41994676, 2026). "A small number of renal cysts is common in this population, which is atypical in PRKCSH- and SEC63-caused ADPLD." (PMID 37628703, 2023). "Inactivation of Sec63 in renal distal tubules selectively activates the IRE1 branch of the UPR and leads to renal cyst formation." (PMID 28437467, 2017).
hepatocellular carcinoma (3 papers, 2012 to 2023). A malignant tumor that arises from hepatocytes. "Herein, we aimed to explore the pivotal roles of SEC63-mediated metabolic remodeling in hepatocellular carcinoma (HCC) cell metastasis after ER stress." (PMID 37122003, 2023). "Altogether, these studies indicate a potential role of SEC63 as a tumor suppressor gene in the carcinogenesis of gastric cancer, colorectal cancer and hepatocellular cancer (HCC) without, however, providing a link of disrupted Sec63 function to tumor cell biology in these entities." (PMID 29263911, 2017).
autosomal dominant polycystic kidney disease (2 papers, 2015 to 2021). Autosomal dominant form of polycystic kidney disease. "In the case of a germline PRKCSH mutation in ADPLD, the second hit could involve a somatic PRKCSH or SEC63 mutation on the other allele, or somatic hits on genes implicated in Autosomal Dominant Polycystic Kidney Disease (ADPKD), such as PKD1 and PKD216." (PMID 26671672, 2015). "XBP-1s is also activated in a polycystin-1 (PC-1)-mediated autosomal dominant polycystic kidney disease (ADPKD) model induced by selective ablation of SEC63 in all distal nephron segments in embryonic stage." (PMID 33671535, 2021).
gastric cancer (2 papers, 2017 to 2024). A primary or metastatic malignant neoplasm involving the stomach. "This study confirmed that lncRNA WFDC21P aggravated gastric cancer malignant behaviors by interacting with SEC63 to regulate the calcium homeostasis signaling pathway." (PMID 38528582, 2024). "SEC63 was also upregulated in gastric cancer and exerted effects during tumor growth and metastasis." (PMID 38528582, 2024). "Further systematic researches revealed that WFDC21P interacted with SEC63 to regulate the calcium homeostasis signaling pathway to facilitate gastric cancer proliferation and metastasis." (PMID 38528582, 2024). "The results showed that SEC63 was upregulated in gastric cancer compared to normal stomach tissues (Figure." (PMID 38528582, 2024). "Our results suggested that the WFDC21P and SEC63 may have prognostic and therapeutic applications in patients with gastric cancer." (PMID 38528582, 2024).
Hepatic cysts (2 papers, 2013 to 2024). "p.Thr2250Met mutation in homozygosity and in combination with SEC63 gene mutations contributed to severe phenotype in a patient with hepatic cysts in comparison with his relatives who had p.Thr2250Met mutation in heterozygous state." (PMID 23496908, 2013).
Kidney Cyst (2 papers, 2023 to 2024). Abnormal fluid filled sac within the kidney, either acquired or congenital. "PKD1 and PKD2 variants are linked to ADPKD regardless of the presence or absence of PLD, while PRKCSH and SEC63 variants are always associated with ADPLD without kidney cysts." (PMID 37761895, 2023).
renal carcinoma (2 papers, 2017 to 2018). A carcinoma arising from the epithelium of the renal parenchyma or the renal pelvis. "From the unique set of genes detected by knnAUC, four genes, APOE, DSC2, SEC63 and SYCP1 were reported to be relevant to renal cancer." (PMID 30466390, 2018). "Out of the unique set of genes detected by BNNPT, a few were reported to be relevant to renal cancer or disease: CDCP1, GSTT1, E2F3, MAPK1, SALL4, SIRT1, ADAMTS13, Gfrα1, ASPH, MIR17HG, APOE, BMP4, RCOR1, NUMB and SEC63." (PMID 28986523, 2017).
gastric tumor (1 paper, 2024). "However, whether SEC63 regulate gastric tumor growth and metastasis remains unknown." (PMID 38528582, 2024).
hereditary non-polyposis colorectal cancer (1 paper, 2021). "Similar results were reported in 2005 and in 2013, where MSI associated SEC63 frameshift mutations were found in 56% of small-bowel cancers in patients with hereditary non-polyposis colorectal cancer (HNPCC) and in one case of hepatocellular carcinoma." (PMID 33925740, 2021).
kidney damage (1 paper, 2022). "Moreover, elimination of both SEC63 and components of the protective IRE1 branch of the UPR lead to more significant kidney damage, suggesting that the UPR is protective in the context of SEC63 deficiency." (PMID 35104250, 2022).
stomach adenocarcinoma (1 paper, 2019). "The stomach adenocarcinoma dataset revealed that overall survival was significantly altered as a result of differential expression of four HSPs - CCT8, DNAJC19, GAK and SEC63." (PMID 30578123, 2019).
Zellweger syndrome (1 paper, 2025). "This problem originally also occurred after transient depletion of PEX3, Sec62, and Sec63 and was the reason for the use of CRISPR/Cas9-mediated Sec62- as well as Sec63-knock-out cells or fibroblasts from PEX3-deficient Zellweger Syndrome patients." (PMID 41009394, 2025).
cancer (7 papers, 2009 to 2025). A tumor composed of atypical neoplastic, often pleomorphic cells that invade other tissues. "Metastasis caused by SEC63 is beneficial for cancer cells to seek new settlements upon ER stress caused by the primary microenvironment." (PMID 37122003, 2023). "Frameshift mutations in SEC63 gene caused by microsatellite instability were uncovered in microsatellite-unstable cancers." (PMID 37122003, 2023). "Sec63 is found to be linked to diabetes, cancers, and autosomal dominant polycystic liver and kidney diseases." (PMID 34884562, 2021). "Taken together, our findings highlight a cancer selective adaption to ER stress as well as reveal the potential roles of the IRE1α-SEC63-ACLY axis in HCC treatment." (PMID 37122003, 2023). "At the same time, SEC63 induces Snail1 expression by increasing acetylation of SMAD3 to promote cancer cell metastasis." (PMID 37122003, 2023). "Importantly, amplification or overexpression of SEC63 was reported to be frequent molecular characteristics of human cancers." (PMID 37122003, 2023). "Lastly, expression levels of Sec62 and Sec63 are found to be altered in various cancer cells." (PMID 34884562, 2021).
tumor (4 papers, 2017 to 2024). "Tumor phenotype assay revealed that SEC63 overexpression rescued the tumor suppressive effect caused by WFDC21P silencing." (PMID 38528582, 2024). "Above results indicate that SEC63 overexpression suppresses the anti-tumor effect caused by interfering WFDC21P expression." (PMID 38528582, 2024). "High frequency of mutation and overexpression of SEC62 and SEC63 have been observed in kinds of cancers, suggesting the potential role of ER protein in tumor development." (PMID 34774014, 2021). "Further mechanism studies reveal that WFDC21P interacted with SEC63 protein to promote tumor malignant behaviors by regulating calcium signaling pathway." (PMID 38528582, 2024). "Importantly, univariate and multivariate Cox regression analyses showed that besides Edmondson Grade, metastasis, and tumor size, the expression of SEC63 was also identified as an independent prognostic indicator for prognosis of HCC patients." (PMID 37122003, 2023).
kidney disorder (2 papers, 2020 to 2024). A disease involving the kidney. "Furthermore, several VUS in known renal disease genes were analyzed by means of retrospective phenotyping or upon complementary DNA (cDNA)-based splice site analysis (GANAB: c.2319G>A, p.Ala773=, PARN: c.1405+3A>G in ID52.1, SEC63: c.1936–8->TTT in ID20.1 and ID97.1), disproving pathogenicity." (PMID 32398770, 2020).
SEC63 also shares sentences with these, for which no sentence is quoted: common variable immunodeficiency (2 papers); neutropenia (2); autosomal dominant tubulointerstitial kidney disease (1); cervical carcinoma (1); channelopathies (1); colorectal cancer (1); congenital disorder of glycosylation (1); diabetes (1); glioblastoma (1); infection (1); infertile (1); Lynch syndrome (1); Obesity (1); tubulointerstitial kidney disease (1).